IL6 (interleukin 6)
Diseases named in the same sentence as IL6 in open-access papers (continued):
Sharing a sentence is not in itself a finding about the gene and the disease.
tumor (continued). "A similar effect is seen in pancreatic cancer, where myeloid-derived IL-6 promotes tumour progression from epithelial precursor lesions through STAT3." (PMID 28210073, 2017). "On the basis of the data we have presented in this report, the selective inhibition of IL-6/STAT3 signalling in the tumour microenvironment provides an attractive target for therapeutic intervention." (PMID 28508871, 2017). "The expression of TNFα, interleukin-6 and C-reactive protein were all increased in the livers of tumor-bearing mice, and KD significantly boosted their expression." (PMID 28915665, 2017). "Increased or deregulated expression of IL6 significantly contributes to the pathogenesis of various human diseases, including tumours." (PMID 29234033, 2017). "STAT3 is hyperactivated in IBC, as demonstrated by a high incidence of phosphorylated STAT3 in tumor tissues and also elevated upstream cytokines such as IL6 known to activate this pathway." (PMID 28107181, 2017). "We analyzed the expression level of IL6 mRNA and IL-6 protein over time in tumor samples and plasma from NB-Tag mice, and noted that its increase correlated with the time of highest macrophage infiltration in the tumors, i.e., > 12 weeks of age." (PMID 29207662, 2017). "Upon secretion from astrocytes, IL-6 facilitates tumor progression through induction of angiogenesis, cell proliferation and resistance to apoptosis." (PMID 28346397, 2017). "Recent studies have highlighted the mechanisms by which the cytokines secreted by inflammatory cells and regulated by the transcription factor NF-κB such as TNF-α, IL-6 and IL-17A stimulate tumor development and progression." (PMID 28881574, 2017). "Taken together, these data indicate that cluster A TAMs are skewed towards alternative activation (CD163), extracellular matrix (ECM) remodeling (PCOLCE2) and promotion of tumor growth (IL-6)." (PMID 28327095, 2017). "Comparably, miR-133b (member of the miR-133 cluster) interferes with paracrine communication of CAFs by interleukin-6 (IL-6) that can promote tumor progression." (PMID 28538690, 2017). "With mounting evidence showing the importance of IL-6 in tumor biology, IL-6 pathway targeting drugs that either block the receptor or binding the ligand have been tested." (PMID 29245982, 2017). "Median serum Shh (=0.001), IL-6 (p = 0.001) levels, tumor burden (p = 0.020), tumor progression (p-0.031), and lymph node status (p = 0.01) were associated with significant prognostic value and early EFS and shorter survival when elevated." (PMID 28496132, 2017). "Indoleamine-2,3-dioxygenase (IDO) and Interleukin-6 (IL-6) contribute to poor therapeutic effects, tumor relapse and aggressive tumor growth." (PMID 29296206, 2017). "In the same animal model, overexpression of TGF-β reduced IL-6 production, delayed tumor development, and inhibited tumor growth." (PMID 28852270, 2017). "Together, current evidence suggests that during cancer cachexia, tumor-secreted IL-6 has an important role in mitophagy regulation." (PMID 28785374, 2017). "On multivariate analysis, tumor grade and IL-6 level remained significant factors of events (p = 0.01 and p = 0.005, respectively)." (PMID 28851899, 2017). "Our results showed a remarkable decrease in multiple proinflammatory cytokines such as TNF-a and IL-6 both in serum and tumor tissue of subcutaneous mouse model, suggesting the inhibitory effect of QRHX on cancer-related inflammation." (PMID 28630636, 2017). "There was limited information for other potential confounders such as smoking habits, history of HPV infection, tumour histology or other serum inflammatory markers such as IL-6 or IL-8." (PMID 28900475, 2017). "This phenomenon supports our finding of prevalent retention/upregulation of IL-6 by CRC epithelial tumor cells." (PMID 29285252, 2017).
tumor (continued). "Further study indicated that QRHX inhibited cancer-related inflammation in tumor by decreasing infiltration of TAMs and IL-6 and TNF-α production and meanwhile decreased arginase 1 (Arg-1) expression and increased inducible NO synthase (iNOS) expression." (PMID 28630636, 2017). "The absence of miR-21 also reduced the expression of inflammatory cytokines (IL-6, IL-23, IL-17A and IL-21) and attenuated the proliferation of tumour cells." (PMID 28099146, 2017). "IL6 is one of the major pro-inflammatory cytokines in the tumor microenvironment, and exhibits tumor-supporting activities." (PMID 29048388, 2017). "The tumor promoting effect of IL-6 is mainly exerted by activation of the oncogenic transcription factors STAT3 and NF-κB, whereas loss of SOCS3 is important for further CAC progression." (PMID 28881611, 2017). "IL-17 and IL-22 enhances IL-23 protumourigenic activity which enhance tumour growth and survival through JAK/STAT3 by activation of IL-6 results in cellular proliferation, angiogenesis, and tumour progression." (PMID 28275390, 2017). "Interleukin-6 (IL-6) plays a key role in a broad spectrum of biologic activities, including malignant transformation and tumor growth." (PMID 29271940, 2017). "High levels of IL-6 were found in the peri-prostatic adipose tissue of tumor-bearing patients and the levels of IL-6 correlated with the aggressiveness of the tumors, highlighting the importance of this cytokine in the adipocyte/cancer cells crosstalk." (PMID 28915700, 2017). "Our study highlights the perspectives of small molecule compounds that target the IL-6-Dub3-Slug/Twist signaling axis with high specificity and efficiency in treatment of tumor metastasis." (PMID 29088851, 2017). "Here, we report that IL-35 can induce N2 neutrophil polarization (protumor phenotype) by increasing G-CSF and IL-6 production, and promote neutrophil infiltration into tumor microenvironment." (PMID 28432279, 2017). "IL-6 and IL-6R have been shown to promote tumor growth, and we previously identified the IL6R gene as one of the inflammation-related genes in a 14-gene prognostic signature in children with high-risk tumors lacking MYCN amplification." (PMID 29207662, 2017). "Radiation-induced IL-6 level increase has also been shown in our previous studies studying the IL-6 effect on promoting macrophage infiltration into tumor sites after radiation." (PMID 29113321, 2017). "Previous studies have shown that the main cytokine in tissue fluid is IL-6, which promotes tumor cell proliferation, invasion, and other biological behaviors via phosphoinositide 3-kinase (PI3K) and other pathways, thereby triggering recurrence and metastasis." (PMID 28968986, 2017). "Inhibition of the constitutively active Jak/STAT3 in gastric tumor leads to reduced polymorphonuclear inflammation and inhibition of pro-inflammatory cytokines IL-11, IL-6 and IL-1β and reduction of tumor volume in mice." (PMID 28350359, 2017). "First, we showed that CR-LAAO induced the release of significant levels of IL-6 and IL-1β after 6 h of stimulation of HL-60 and HepG2 tumor cells." (PMID 28205610, 2017). "IL-6 is secreted by many different cells, including T cells, B cells, monocytes, endothelial cells, fibroblasts, and some tumor cells." (PMID 29245982, 2017). "Regression analysis of the tumor growth rates showed that IL-6 knockout in the endothelial cells was sufficient to slow down xenograft tumor growth." (PMID 29245982, 2017). "We found that IL-6 secreted by tumor cells accelerates autophagy in myotubes when complexed with soluble IL-6 receptor (trans-signaling)." (PMID 28515477, 2017). "The cytokines like IL-12 and IFNγ have an anti-tumor role, while the cytokines like IL-6, IL-17, and IL-23 are pro-tumor." (PMID 28337150, 2017). "Tumor microenvironmental factors, such as leukemia inhibitory factor, IL-6, and M-CSF, were shown to promote TAM generation." (PMID 28970834, 2017).
tumor (continued). "In contrast, genetic ablation of Il6 resulted in a significant decrease in FGF19-induced tumour multiplicity, tumour size and glutamine synthetase-positive tumour area." (PMID 28508871, 2017). "To further confirm the anti-inflammatory effects of L-4F, we analyzed mRNA levels of the inflammatory cytokines IL-17A, IFN-γ, IL-6, and IL-1β in tumor tissues from Sc-4F- or L-4F-treated tumor-bearing mice." (PMID 29245934, 2017). "Tumor cells can also produce the thrombopoietic cytokine interleukin-6, which affects cell proliferation and stimulates the differentiation of megakaryocytes to platelets in the bone marrow." (PMID 29069863, 2017). "Serum cytokine analysis suggested that neither 70 mg/kg/day of SSZ nor 20 mg/kg/day of 5-ASA were effective at preventing the increase in IL-6 that was induced by tumour burden." (PMID 28120908, 2017). "TNF-α and IL-6, expressed in the tumor microenvironment, are important for the development of inflammation-associated intestinal tumorigenesis." (PMID 27679575, 2016). "TNF-α and IL-6 produced by the immune infiltrate and tumor cells are also considered as master switches between inflammation and cancer sustaining cellular transformation, survival, proliferation, angiogenesis, and metastasis." (PMID 27886105, 2016). "We therefore also analyzed IL-6 as possible further intrinsic tumor cell trigger for regulating the expression of PD-L1 after radiation and chemoradiation." (PMID 28066420, 2016). "In inflammatory cells, the NFκB pathway results in the induction of numerous tumor-promoting chemokines and cytokines such as IL-6, TNF-α, IL-1β, CXCL8, VEGF, and CSF-1." (PMID 26980947, 2016). "We observed that the diagnostic sensitivity of IL-6 and M-CSF was also higher than those of CEA and SCC-Ag and increased in combined use with classical tumor markers for EC." (PMID 27041792, 2016). "Collectively, our results demonstrate for the first time that the IL-6/STAT3 signaling axis is a key element of tumor-stromal interaction between PSCs and tumor cells, playing a critical role in the progression from pre-neoplastic PanINs to PDAC." (PMID 27602757, 2016). "We also investigated the correlation between IL-6 and PD-L1 expression and their effects on tumor immune response to provide new insights into the development of immune-based therapy." (PMID 26761210, 2016). "The results demonstrate PDTC treatment improved muscle protein turnover and liver glycogen content independent to changes in circulating IL-6 and tumor burden." (PMID 27449092, 2016). "One of the best surrogates of chronic inflammation in the pathogenesis of tumor is interleukin-6 (IL-6), a pleiotropic inflammatory cytokine." (PMID 27383632, 2016). "Emerging evidence shows that IL-6 plays critical roles in cancer development, progression and metastasis by regulating the tumor microenvironment and cancer stem cells." (PMID 26840088, 2016). "High levels of pro-inflammatory factors in the microenvironment of the tumour, such as GM-CSF, IL-1b, IL-6, and S-100, induce the recruitment and expansion of myeloid-derived suppressor cells, increasing pro-tumour activity." (PMID 26913068, 2016). "Tumors were subsequently excised from mice and H & E stain confirmed tumor phenotypes of IL-6 expression." (PMID 26675547, 2016). "BrdU staining with subcutaneous mouse tumors demonstrated that IL-6-treated tumor tissues had significantly higher numbers of BrdU-positive nuclei than control group." (PMID 27769047, 2016). "The finding that tumor-induced IL-6 suppresses PPARalpha-regulated ketogenesis was confirmed mechanistically, in vivo, through both gain- and loss-of-function studies." (PMID 27829137, 2016). "Chronic inflammation is one of the important factors of carcinogenesis, in which the inflammatory mediators such as TNFα, IL-1β and IL-6 secreted by macrophages promote tumour growth by deregulating the cell cycle checkpoints and cell repair machinery." (PMID 27270308, 2016).
tumor (continued). "To analyze the effect on tumor growth of inhibiting IL-6 signaling, we used two alternative therapies: anti-IL-6 and anti-IL6RA blocking antibodies." (PMID 27602583, 2016). "A large amount of molecules released by tumor cells or tumor-surrounding cells, including IL-1β, IL-4, IL-6, IL-10, IFN-γ and TGF-β, are reported to re-program immature myeloid cells to become immunosuppressive." (PMID 26967390, 2016). "In support of the important role of IL-6 in promoting cancer growth in the bone marrow, blockade of IL-6 by neutralizing antibody as well as inhibition of JAK2 by small-molecule inhibitors significantly blocked tumor growth." (PMID 27049717, 2016). "Ovearll, these data attribute to Notch a function in MM pathogenesis as a key signaling pathway in tumor-stroma communication exploited by MM cells to shape the BM niche and specifically to increase the release of a key cytokine such as IL-6." (PMID 27463014, 2016). "Theoretically, dynamic changes in the SIR resulting from tumor-host interactions are best estimated by directly measuring the serum IL-6 level." (PMID 27650456, 2016). "Several studies have reported that JAG1 mediates multiple signaling pathways such as: AP-1, MAPK, EGFR, NF-κβ, and IL-6 in different tumor cells." (PMID 26930648, 2016). "Tumor-associated macrophages and myeloid suppressive cells represent tumor-promoting immune cells together with their derived cytokines IL-6, IL1β, IL23 and TNFα." (PMID 27608835, 2016). "Secretion of IL-6 leads to recruitment of metastatic cells out of the circulation to the primary tumor sites." (PMID 27756885, 2016). "Compelling evidence suggests that IL-6 signaling in the tumor microenvironment is an essential factor promoting tumor cell proliferation, survival, and metastasis." (PMID 26372664, 2016). "Although there are no significant changes in the expression of pro-inflammatory cytokines, such as TNF-α, TGF-β, INF-γ and IL-6, we found a significant overexpression of the anti-inflammatory cytokine IL-10 within the tumor mass of B1−/− mice." (PMID 26898917, 2016). "Compared with control and tocilizumab-treated tumours, TamR tumours not only had higher numbers of CD133hi cells but also had reduced ER expression, increased circulating IL6 levels and elevated Her2 expression." (PMID 26858125, 2016). "We also show that suppressing IL-6 or inhibiting the STAT3 pathway significantly decreases CTC seeding in primary tumours." (PMID 26623559, 2016). "Recently, IL-6 is reported to play a positive role in regulating AKT/PI3K activity to promote tumor cell survival." (PMID 27285760, 2016). "We recently utilized a conditionally immortalized line of murine LECs (SV-LECs) and showed that IL-6 induces VEGF-C expression not only in tumor cells but also in LECs." (PMID 27383632, 2016). "The binding of IL-6 to its receptor gp130 activates JAK2 which goes on to activate several downstream tumor promoters such as STAT3." (PMID 27756885, 2016). "It is also a well-known fact that STAT activation is generally mediated by members of the JAK family of tyrosine-kinases via stimulation of NF-κB regulated genes such as IL-6, IL-10 and IFNγ which are produced by tumor cells in an autocrine manner." (PMID 26998758, 2016). "For example, although IgM+ lymphoproliferation including LPL-like neoplasia was fully penetrant in BCL2+IL6+AID− mice, serum IgM levels were low compared with patients with WM and serum IgM spikes were rarely seen." (PMID 27813533, 2016). "IL-6 is a 23- to 30-kDa pleiotropic cytokine that is produced by various types of cells, including immune cells, fibroblasts, and certain tumor cells." (PMID 26840088, 2016).
tumor (continued). "IL‐6/IL‐17 production is increased in 4THM tumors themselves, and in exosomes from tumor‐bearing mice." (PMID 26725371, 2016). "Blockade of this IL-6 loop by an IL-6 antagonist, tocilizumab, reduced the cancer stem cell population, resulting in decreased tumor growth and metastasis in mouse xenografts." (PMID 26840088, 2016). "By affecting DCs, tumor exosomes facilitate an increase in STAT3phosphorylation and IL-6 expression and, therefore, reduce both the activityand the number of DCs by inhibiting the differentiation of CD14+monocytes into immature DCs." (PMID 27795841, 2016). "Similar to NF-kB, STAT3 is constitutively activated in both tumor and immune cells increasing tumor cell proliferation, survival and invasion and is activated by NFkB-induced genes such as Interleukin 6 (IL6)." (PMID 27349385, 2016). "Next, Zaki and colleagues showed that CNTO 328 (Siltuximab), a monoclonal antibody against IL-6, inhibited human tumor-induced cachexia in Nude mice." (PMID 27330885, 2016). "Recent evidence suggests that MSCs coordinate with tumor cells that triggers increased IL-6 production, which correlates with accumulation of MSCs." (PMID 27756885, 2016). "When blocking IL-6, tumor progression was partially reversed indicating that the protumor activity of IL-17 needs IL-6 in a STAT3-dependent pathway." (PMID 27589729, 2016). "The role of IL-6 as critical mediator for tumor growth, metastasis, and drug resistance in tumor micro-environment was therefore suggested." (PMID 27285760, 2016). "We observed that IL-6 treatment significantly increased tumor sphere formation in normal (PrECs) and ESE3KD prostate epithelial cells compared to vehicle treated cells." (PMID 27732936, 2016). "Complimentary marking of IL-6 with the standard tumor marker SCCAg, especially for patients in the early stages of clinical development, increases its diagnostic sensitivity." (PMID 26289850, 2016). "Our data depict that in dependence on the tumor entity and time after treatment, the surface expression of PD-L1 differs and is partially linked with IFN-gamma expression and IL-6 release." (PMID 28066420, 2016). "The authors additionally found that DCIS cells preferentially migrate towards TAFs and form heterocellular contacts with TAFs driven by an IL-6 expression gradient at the invasive edge of DCIS tumor spheroids." (PMID 27515302, 2016). "Their results also show that GNA12 stimulates the expression and activity of tumor promoting cytokines IL-6 and IL-8 and MMP-2 via binding and activation of NF-kB." (PMID 27551323, 2016). "Both autocrine and paracrine actions of IL-6 in the tumor microenvironment are reported to be critical for breast oncogenesis." (PMID 26840088, 2016). "While tocilizumab treatment inhibited C3HBA tumor growth both in Chy and wt mice, the substantially higher IL-6 level in Chy tumors indicates that this cytokine is relevant for the accelerated tumor growth observed." (PMID 27329584, 2016). "It is believed that IL-6’s pleiotropic tumor-promoting activities are attributable to JAK2-STAT3 signaling cascade." (PMID 27383632, 2016). "The synthesis and secretion of cytokines and chemokines that are known to mediate MSCs' tumor-stimulating and immunosuppressive effects, i.e., IL-6, MCP-1 and IL-10, were down-regulated in lal−/− MSCs." (PMID 27531897, 2016). "Yan et colleagues have also reported that IL-6 cooperates with G-CSF to induce tumor function of murine neutrophils in BM by modulating signaling pathways that favor tumor angiogenesis through up-regulation of PROK2." (PMID 26967390, 2016). "In the present work, we demonstrated that Rhus coriaria inhibited the NFκB signaling through downregulation of phospho-p65 as well as its downstream targets (MMP-9, VEGF, IL-6 and IL-8), all of which are involved in tumor metastasis." (PMID 26888313, 2016). "IL-6 positive carcinoma cells were 50 % in these tumor cells which include the adenocarcinoma component." (PMID 27659803, 2016).